CLOCK (clock circadian regulator)
Diseases named in the same sentence as CLOCK in open-access papers (continued):
Sharing a sentence is not in itself a finding about the gene and the disease.
cardiomyopathy (1 paper, 2021). A disease of the heart muscle or myocardium proper. "Aging female mice do not develop cardiomyopathy, even when the circadian rhythm is disrupted due to CLOCK gene mutation." (PMID 34066863, 2021).
cervical cancer (1 paper, 2023). A primary or metastatic malignant neoplasm involving the cervix. "Significant downregulation of the core circadian clock genes, CLOCK, BMAL1, PER1, CRY1, REV-ERBα, and RORα, was found in cervical cancer tissue specimens and in high-grade squamous intraepithelial lesions compared to the normal cervical epithelium." (PMID 37240325, 2023).
coagulation disorders (1 paper, 2022). "Among these, BMAL2 regulates the transcription of anticoagulant thrombomodulin and PAI-1 by forming a heterodimer with CLOCK; therefore, abnormal expression of BMAL2 may cause coagulation disorders." (PMID 36561297, 2022).
colon adenocarcinoma (1 paper, 2021). "Compared to normal skin, patients with skin cutaneous melanoma (SKCM) present significant down-regulation in the expression of BMAL1, CRY1, CRY2, PER1, PER2, and PER3, and higher expression of CLOCK, a similar pattern was also observed in patients with colon adenocarcinoma (COAD)." (PMID 34966277, 2021).
congenital cataracts (1 paper, 2010). "Thus, both CLOCK and BMAL1 play an important role in lens physiology, strongly arguing that regulation of BMAL1:CLOCK transcriptional activity may be used for the prevention or treatment of age-dependent and possibly congenital cataracts." (PMID 21149897, 2010).
diabetes insipidus (1 paper, 2021). A disorder characterized by excretion of large amounts of urine, accompanied by excessive thirst. "Mice with a knock-out or mutated CLOCK gene have lower blood pressure, plasma aldosterone levels, changed urinary sodium excretion, and a higher incidence of diabetes insipidus than control mice." (PMID 34066863, 2021).
dilated cardiomyopathy (1 paper, 2022). Cardiomyopathy which is characterized by dilation and contractile dysfunction of the left and right ventricles. "A cardiomyocyte-specific CLOCK dominant-negative mutant holds some degree of similarity to the cardiomyocyte-specific Bmal1 knockout, including hypertrophy, impaired metabolism, and loss of gene expression rhythmicity, but does not progress to the lethal dilated cardiomyopathy." (PMID 36062878, 2022).
fibromyalgia (1 paper, 2022). A chronic disorder of unknown etiology characterized by pain, stiffness, and tenderness in the muscles of neck, shoulders, back, hips, arms, and legs. "We also found significant enrichment in patients with variants in CLOCK who also had been diagnosed with fibromyalgia." (PMID 36517845, 2022).
hypertriglyceridemia (1 paper, 2021). A laboratory test result indicating elevated triglyceride concentration in the blood. "In addition, another study with mice that were CLOCK gene mutants (with hyperphagia during their sleep/inactivity phase) showed increased weight gain and hypertriglyceridemia." (PMID 34578912, 2021).
hypoxic ischemic encephalopathy (1 paper, 2022). "Regarding other circadian rhythm-related miRNAs selected in our study, miR-182 targets CLOCK, and dysregulation of this miRNA is a potential reason for circadian rhythm disorder in children with hypoxic ischemic encephalopathy events." (PMID 35329950, 2022).
injury (1 paper, 2017). Damage inflicted on the body as the direct or indirect result of an external force, with or without disruption of structural continuity. "MiR-182 plays important roles in the synaptic connectivity of photoreceptors and retinal regeneration, and a literature described that miR-182 plays a role in regulating CLOCK expression after hypoxia-ischemia brain injury." (PMID 28442995, 2017).
keloid (1 paper, 2025). An irregularly shaped, elevated mark on the skin caused by deposits of excessive amounts of collagen during wound healing. "Among these, CLOCK was identified as a critical regulatory factor in fibroblasts within keloid tissues, and further analysis of the TCGA database revealed elevated expression of CLOCK and its downstream genes in skin tumors." (PMID 41350567, 2025). "Further, CLOCK was found to be predominantly expressed in keloid tissues, with its upregulation enhancing fibroblast proliferation and migration in vitro." (PMID 41350567, 2025). "Further functional studies revealed that CLOCK was mainly expressed in keloid tissues and its upregulation can directly increase the proliferation and migration of fibroblast." (PMID 41350567, 2025). "Notably, pivotal regulators for each sub-fibroblast cluster were discovered: IRF4 for scar, CLOCK for keloid, RUNX3 for scleroderma, and HOXC4 for normal skin." (PMID 41350567, 2025). "Above all, our data indicated that CLOCK might play critical roles in the development and progression of keloids and skin fibrotic tumors." (PMID 41350567, 2025). "Additionally, we identified the pivotal regulators of each specific sub-fibroblast cluster, including IRF4 for scar-related, CLOCK for keloid-related, RUNX3 for scleroderma-related, and HOXC4 for normal skin sub-fibroblast clusters." (PMID 41350567, 2025).
leiomyosarcoma (1 paper, 2018). An uncommon, aggressive malignant smooth muscle neoplasm, usually occurring in post-menopausal women. "Employing an additive model of inheritance CLOCK rs1801260 and PER2 rs934945 were statistically significantly associated with liposarcoma, while NPAS2 rs895520 and RORA rs339972 were statistically significantly associated with leiomyosarcoma." (PMID 30518396, 2018).
lipid metabolic disorders (1 paper, 2023). "With age increased, Egr-1 rhythm alteration might result in the uncoupling of Egr-1 with both circadian genes BMAL1/CLOCK and lipid metabolic genes Cidea, which results in the decoupling of liver circadian and lipid metabolic disorders in ageing mice." (PMID 36964140, 2023).
liposarcoma (1 paper, 2018). A usually painless malignant tumor that arises from adipose tissue. "The present analysis suggested that carriers of the minor allele of the CLOCK polymorphism rs1801260 (C) or of PER2 rs934945 (T) had a reduced predisposition to sarcoma (26% and 35% respectively with the additive model) and liposarcoma (33% and 41% respectively)." (PMID 30518396, 2018). "Since it has been proposed that liposarcoma could arise from the dedifferentiation of fat cells, one could hypothesize a specific role of CLOCK and PER2 genes and this aspect, worth to be investigated, could open the avenue to new therapeutic targets." (PMID 30518396, 2018).
liver fibrosis (1 paper, 2023). "Here, we showed in vitro and in vivo that liver fibrosis is significantly increased when circadian rhythm is disrupted by CLOCK mutation." (PMID 37371052, 2023).
lung adenocarcinoma (1 paper, 2024). A carcinoma that arises from the lung and is characterized by the presence of malignant glandular epithelial cells. "We found that high levels of CLOCK were positively associated with advanced clinical stages and metastasis status of lung adenocarcinoma (LUAD) based data in UALCAN Network." (PMID 39054537, 2024).
lymphoma (1 paper, 2016). A malignant (clonal) proliferation of B- lymphocytes or T- lymphocytes which involves the lymph nodes, bone marrow and/or extranodal sites. "Encouraged by the inverse correlation of MYC with BMAL1 and CLOCK expression in U2OS cells, we assessed expression of these genes in human lymphoma by analysing RNA-seq data of 102 patient samples." (PMID 27339797, 2016). "Consistent with our observation in U2OS cells, expression of both clock genes correlated inversely with MYC levels in human lymphoma (Pearson coefficient −0.61 and −0.37 for BMAL1 and CLOCK, respectively; n=102), whereas MYC-activated genes such as NCL and NCLN showed a positive correlation." (PMID 27339797, 2016).
malaria (1 paper, 2025). Malaria is a serious and sometimes fatal disease caused by a parasite that commonly infects a certain type of mosquito which feeds on humans. "While homologs of BMAL1 and CLOCK have not been identified in malaria parasites or other protozoan parasites, the existence of intrinsic rhythms in these organisms could be through the use of alternative transcription factors or pathways to establish similar feedback mechanisms." (PMID 41130920, 2025).
male infertility (1 paper, 2013). The inability of the male to effect fertilization of an ovum after a specified period of unprotected intercourse. "In the case-control study we found evidence of an association between male infertility and gene variants of the CLOCK gene in a sample of 961 men." (PMID 23527142, 2013). "We provide evidence that genetic variability in the CLOCK gene might be associated with male infertility warranting further confirmation and mechanistic investigations." (PMID 23527142, 2013). "However, we did not, find any significant association between rs13124436 polymorphism from CLOCK gene and male infertility." (PMID 23527142, 2013). "In conclusion, we provide evidence that genetic variability in the CLOCK gene might be associated with male infertility, and consequently imply the role of the circadian timing system in human reproduction." (PMID 23527142, 2013). "We performed a case-control study, where we searched for an association between polymorphisms of CLOCK and ARNTL genes and male infertility in 961 Slovenian and Serbian Caucasian men." (PMID 23527142, 2013). "Therefore, we hypothesized that genetic variability of the CLOCK and ARNTL genes may be associated with male infertility in humans." (PMID 23527142, 2013). "The aim of this study was to examine whether there is an association between genetic variability in the primary clock genes CLOCK and ARNTL and male infertility in humans." (PMID 23527142, 2013).
manic episodes (1 paper, 2016). "The CLOCK 3111T/C single-nucleotide polymorphism (SNP; rs1801260) is a genetic variation of the human CLOCK gene that is significantly associated with increased frequency of manic episodes in BD patients." (PMID 27148095, 2016).
medulloblastoma (1 paper, 2025). A malignant, invasive embryonal neoplasm arising from the cerebellum. "The differential expression of CLOCK among the four major medulloblastoma (MB) subgroups was observed across multiple datasets." (PMID 40002179, 2025).
metastatic cancer (1 paper, 2025). A carcinoma which has spread from the original site of growth to another anatomic site. "The results showed that the expression levels of CLOCK, along with CBX5, CHN1, CNN3, FNDC1, PALLD, and SULF1, were significantly elevated in metastatic cancer tissues compared to primary cancer tissues." (PMID 41350567, 2025).
metastatic colorectal cancer (1 paper, 2020). "Polymorphisms in the CLOCK sequence and the expression levels of miRNAs regulating the clock-genes were associated with longer overall survival of females with metastatic colorectal cancer compared to males." (PMID 33363037, 2020).
metastatic tumors (1 paper, 2025). "Analysis of The Cancer Genome Atlas (TCGA) data revealed that CLOCK and its regulon genes were upregulated in skin cutaneous melanoma and even more so in metastatic tumors." (PMID 41350567, 2025).
Miscarriage (1 paper, 2017). A pregnancy that ends at a stage in which the fetus is incapable of surviving on its own, defined as the spontaneous loss of a fetus before the 22th week of pregnancy. "CLOCK knock-down leads to reduction in reproduction and increased miscarriage risk in female mice, and CLOCK mutation reduces the implantation capacity of mice." (PMID 29163762, 2017).
mucopolysaccharidosis type 2 (1 paper, 2013). A lysosomal storage disease leading to a massive accumulation of glycosaminoglycans and a wide variety of symptoms including distinctive coarse facial features, short stature, cardio-respiratory involvement and skeletal abnormalities. "After 24 hours of treatment with idursulfase in fibroblasts of patients with Mucopolysaccharidosis type II the expression evaluated by NGS of the genes CLOCK, ARNTL2, NR1D1, NR1D2, and TIMELESS showed higher expression levels compared to untreated HS fibroblasts." (PMID 24083598, 2013). "ARNTL, the heterodimerization partner of CLOCK and NPAS2, enhances their enzymatic function, and the decreased expression of these central components of the molecular clock could hinder the correct clock gene expression in the fibroblasts of Mucopolysaccharidosis type II patients." (PMID 24083598, 2013).
nephrolithiasis (1 paper, 2016). The presence of a calculus in the pelvis of the kidney; this is most often composed of mineral salts and proteins. "This percentage may increase by screening nephrolithiasis patients for mutations in USP2 or in clock genes controlling its expression such as ARNTL (BMAL1) and CLOCK and their binding sites in the promoter of USP2." (PMID 26756164, 2016).
non-small cell lung carcinoma (1 paper, 2024). A group of at least three distinct histological types of lung cancer, including non-small cell squamous cell carcinoma, adenocarcinoma, and large cell carcinoma. "Chronic stress-induced NE caused resistance of oral or non-small cell lung cancer cells to cisplatin, we investigated the effect of CLOCK deficiency on the sensitivity of NCI-H1299 to chemotherapy by measuring the viability and proliferation of the cells subjected to NE treatment." (PMID 39054537, 2024).
nonalcoholic fatty liver disease (1 paper, 2020). "In patients with nonalcoholic fatty liver disease (NAFLD), single nucleotide polymorphisms in the circadian gene CLOCK (rs1801260) and PPARγ (rs3856806) are highly prevalent." (PMID 32093272, 2020).
osteoarthritis (1 paper, 2021). A noninflammatory degenerative joint disease occurring chiefly in older persons, characterized by degeneration of the articular cartilage, hypertrophy of bone at the margins and changes in the synovial membrane. "The most exciting finding of this study may be the therapeutic potential of CLOCK expression vector in reversing cellular senescence and treating age-related disorders such as osteoarthritis." (PMID 32737416, 2021).
ovarian dysfunction (1 paper, 2022). The inability of the ovaries to function. "CLOCK, BMAL1, and E4BP4 can be entrained by hypoxic signaling, which synergistically promotes LHCGR reduction in GCs and results in ovarian dysfunction." (PMID 36620217, 2022).
ovarian endometriosis (1 paper, 2012). A non-neoplastic disorder characterized by the growth of endometrial tissue in the ovaries. "Dys-regulation of three (CLOCK, ESR1, and MYC) major transcription factors appeared to be significant causative factors in the pathogenesis of ovarian endometriosis." (PMID 23006437, 2012).
parasite infection (1 paper, 2022). "The results were striking, showing that CLOCK silencing can reverse the parasite infection outcome." (PMID 36454885, 2022).
periodontitis (1 paper, 2022). An acute or chronic inflammatory process that affects the tissues that surround and support the teeth. "Periodontitis in adults resulted in decreased levels of CSNK1D, RORA, CLOCK, DBP, NR1D1, ID2, and PER3 and a substantial increase in expression of FOS." (PMID 36472983, 2022).
psychotic disorder (1 paper, 2015). An abnormal condition of the mind that involves a loss of contact with reality. "For example, disturbed sleep has been implicated in the disruption of transcripts associated with CLOCK genes, which have tentatively been linked with psychotic disorders (Lamont, Coutu, Cermakian, & Boivin, 2010)." (PMID 25938536, 2015).
renal fibrosis (1 paper, 2025). A final common manifestation of a wide variety of chronic kidney diseases characterized by glomerulosclerosis and tubulointerstitial fibrosis. "TGFβ-dependent renal fibrosis was observed in CLOCK-deficient mice compared to wild-type counterparts, with increased fibrosis attributed to elevated COX2 expression." (PMID 39940247, 2025).
sarcopenia (1 paper, 2024). Progressive decline in muscle mass due to aging which results in decreased functional capacity of muscles. "Disrupted circadian rhythms, regulated by genes such as BMAL1 and CLOCK, are associated with both LBW and sarcopenia, impacting lipid metabolism, muscle mass, and the ageing process." (PMID 38553412, 2024). "Disrupted circadian rhythms, regulated by genes known as BMAL1 and CLOCK, are linked to both LBW and sarcopenia, impacting lipid metabolism, muscle mass, and ageing processes." (PMID 38553412, 2024).
septic shock (1 paper, 2021). Shock caused by infection; frequently caused by gram negative bacteria, although some cases have been caused by other bacteria, viruses, fungi, and protozoa; characterized by fever, chills, tachycardia, tachypnea, and hypotension. "In summary, the positive regulators of the transcriptional–translation feedback loop (CLOCK and ARNTL) were the least rhythmic, while negative regulators (NR1D1, NR1D2, CRY2) were the most rhythmic in septic shock patients." (PMID 33900485, 2021).
skin cancer (1 paper, 2025). "Further database analyses indicated an increase in the expression levels of CLOCK and its downstream genes in metastatic skin cancers." (PMID 41350567, 2025). "Expanding our investigation to the expression of CLOCK and its ten key regulated genes in skin cancer and metastatic samples, we utilized TIMER2.0 for analysis." (PMID 41350567, 2025).
thrombosis (1 paper, 2022). "Mice with downregulated CLOCK gene expression were reported to have longer PT and APTT and were less likely to develop thrombosis." (PMID 36292752, 2022).
thyroid (1 paper, 2021). "We then chose CLOCK, BMAL1, CRY1, CRY2, PER1 and PER2 to observe the changes of circadian rhythm genes in thyroid malignant tissues." (PMID 34211057, 2021). "The expression levels of CLOCK, BMAL1 and PER2 in thyroid malignant group were significantly higher than benign and normal groups, while CRY2 was decreased, p < 0.05." (PMID 34211057, 2021).
tongue cancer (1 paper, 2016). A malignant neoplasm affecting the tongue. "Considering this, cultured tongue cancer cells and control cells were synchronized and used to confirm the relationship between BMAL1/CLOCK and PFKFB3." (PMID 27079271, 2016). "Of interest, the expression of key clock genes was either down-regulated, e.g., BMAL1, CLOCK, PER1, PER2, and PER3, or up-regulated, e.g. CYR1 and CRY2, in tongue cancer samples in relative to that in normal control samples." (PMID 27079271, 2016). "In the in vitro systems, SCC9 tongue cancer cells displayed rhythmic expression of PFKFB3 and CLOCK that was distinct from control KC cells." (PMID 27079271, 2016). "However, the down-regulation of BMAL1 and CLOCK expression and the up-regulation of PFKFB3 expression in tongue cancer samples do not necessarily imply that BMAL1 and/or CLOCK down-regulation leads to increased PFKFB3 expression." (PMID 27079271, 2016).
triple-negative breast carcinoma (1 paper, 2020). An invasive breast carcinoma which is negative for expression of estrogen receptor (ER), progesterone receptor (PR), and human epidermal growth factor receptor 2 (HER2). "Our data showed that knockdown of ASMT in triple-negative breast cancer cells significantly reduced cell migration and invasion, but this phenotype was reversed when CLOCK was over-expressed simultaneously." (PMID 33194597, 2020).